ALB (albumin)
Diseases named in the same sentence as ALB in open-access papers (continued):
Sharing a sentence is not in itself a finding about the gene and the disease.
tumor (continued). "Considering the importance of albumin, a number of putative albumin-binding proteins and receptors have been identified in various tissues and cell lines, including kidney, endothelium, fibroblasts, and tumor-cell surfaces." (PMID 25161624, 2014). "However, we have identified that tumor recurrent status, the number of tumors, albumin (ALB), prothrombin time (PT) and platelet count (PLT) were significantly associated with poor overall survival in HCC patients receiving RFA combined with TACE." (PMID 24586515, 2014). "Overall, the C-KIT+/EpCAM+/E-cadherin+/K7−/K19−/AFP−/albumin− immunotype suggested that the present tumor may have originated from transformed C-KIT+/EpCAM+ DE-like cells, which are more primitive and undifferentiated than bipotential HPCs." (PMID 25202388, 2014). "Flow cytometric analysis showed that albumin + cells of the original tumor #21 were 83.2%." (PMID 25349534, 2014). "Multivariate linear regression analysis showed that, among CRC patients, serum levels of NGAL significantly decreased with serum albumin (p < 0.001) and were positively associated with WHR (p = 0.005), recent weight loss >5 kg (p = 0.026) and maximal tumor size (p = 0.028)." (PMID 25472811, 2014). "Thus, albumin immunoreactivity was employed in this study to assess the integrity of the BBB over the 4 weeks following tumor cell inoculation." (PMID 24818961, 2014). "Albumin-bound paclitaxel is known to increase intratumoral concentration of paclitaxel by a receptor-mediated transport process across the endothelial cell wall, thereby breaching the blood/tumor interface." (PMID 24804130, 2014). "In addition, albumin has been shown to be taken up by cells in the injured brain and by growing tumour tissue, possibly as a source of amino acids and energy or as a by-product of uptake for albumin-bound metabolically important ligands." (PMID 25211495, 2014). "A drug that interacts sufficiently strong with albumin may be concentrated within the cancer tissue through the tumor specific process known as the enhanced permeability and retention (i.e., EPR) effect." (PMID 25193858, 2014). "Albumin-bound paclitaxel is known to increase intratumoral concentration of the paclitaxel by a receptor-mediated transport process across the endothelial cell wall, thereby breaching the blood/tumor interface." (PMID 24804130, 2014). "Univariate analysis identified the following prognostic risk factors in the total population: tumor number ≥3, serum AFP ≥400 ng/mL, serum albumin <4 g/dL, serum alanine aminotransferase >80 U/L, serum bilirubin >1.2 mg/dL, macrovascular invasion, major hepatectomy, and PHT." (PMID 25268959, 2014). "NAB-paclitaxel may act as a “Trojan horse,” with the albumin encapsulation serving to direct the paclitaxel chemotherapeutic agent to tumor cells via binding to SPARC." (PMID 24484617, 2014). "In addition, IC7-1-Bu enabled clear in vivo tumor imaging through serum albumin mediated transport, which has emerged as a versatile drug delivery carrier for therapeutic and diagnostic agents that diagnose and treat cancers 22–24." (PMID 24737784, 2014). "Furthermore, it has been shown to bind with high affinity to albumin, which raised some interest in its possible role in improving the delivery of albumin-bound cytotoxics to the tumor." (PMID 23638089, 2013). "Neither CRCTU nor ATCC Walker 256 tumour injection into the internal carotid artery caused a significant increase in albumin immunoreactivity 24 h following surgery, when compared to the culture medium control group." (PMID 23374226, 2013). "Strong albumin immunoreactivity was observed within GG specimens in tumor astrocytes." (PMID 23347564, 2013). "Serum albumin may be an indicator of a complex process involving tumour induced and pro-inflammatory factors that affect survival rather than a previously thought marker of nutritional status alone in these patients." (PMID 23590192, 2013).
tumor (continued). "Astrocytes and microglia may proliferate and become activated in response to contact with serum proteins, such as albumin which is present in oedematous fluid that accumulates around the tumour." (PMID 23374226, 2013). "Univariate analysis revealed that age >47 years old, tumor size >3 cm, alpha-fetoprotein >8 ng/mL, albumin ≤4 g/dL, AST >42 U/L, ALT >50 U/L, AST/ALT >0.89, presence of occult HBVCI, and absence of overt HBVCI were associated with a shorter disease-free survival." (PMID 23805180, 2013). "Evens blue-Albumin could extravasate leaky tumor vessels and the time when clearly shown vessels became blurry was defined as the point when Evans blue-Albumin extravasated from tumor vessel into tumor parenchyma." (PMID 23799045, 2013). "Furthermore, albumin levels, resection margin status, tumor stage and histological differentiation can be used as prognostic factors for survival after resection of PCA." (PMID 22559838, 2012). "However there is increasing evidence that the presence of cancer cachexia, partly reflected by a reduction in albumin, is driven by a sustained inflammatory response, either from the tumour itself or as a host reaction." (PMID 22433965, 2012). "However, when these confounding factors were included, multivariate analysis showed that tumor number >1, macrovascular invasion, albumin ≤ 4.0 g/dL, and furin expression T/N ratio <3.5 were independent factors correlated with a shorter DFS." (PMID 22808247, 2012). "Interestingly, in addition to well-established indicators of survival, such as resection margin status, tumor stage and histological differentiation, we identified serum albumin as an independent prognostic factor after resection of PCA in our study." (PMID 22559838, 2012). "We then looked at whether albumin (∼65 kDa), which is a larger molecule than the CA, could also be delivered to tumor sites by modulating BTB permeability with NG29." (PMID 22629405, 2012). "Furthermore, albumin-based nanoparticle delivery systems are easily accumulated in tumor tissue due to the enhanced permeability and retention (EPR) effect." (PMID 22187654, 2012). "Albumin-bound Evans Blue was visualized on tumour vibratome slices and again could only be detected in the near vicinity of blood vessels." (PMID 22590529, 2012). "The same specific uptake of albumin into inflamed joints of mice in the collagen induced arthritis model as into tumour tissue was seen, emphasizing the similarity of physiological processes in inflammation and tumour growth, such as an increased catabolism of proteins." (PMID 21676260, 2011). "This appears to be secondary to a reduction in albumin that may be secondary to a number of factors, including operative management, adjuvant oncological therapies or tumour progression, a pattern recognized in previous studies within specific tumour types." (PMID 20717110, 2010). "At the same time, enhanced tumor vascular permeability in these regions drives extravasation of macromolecules such as serum albumin (SA) from the circulation into the tumor tissue, while the poor lymphatic drainage fosters their retention within the tumor compartment." (PMID 20497549, 2010). "As one of the last speakers, Eva Frei explained how albumin can be used to transfer and accumulate drugs or other compounds into tumour tissues; concerning the binding of insulin detemir (Levemir®) to albumin after subcutaneous injection, a paucity of data was noted in this respect." (PMID 21176129, 2010). "Finally, treatment of Balb/c mice with testosterone albumin conjugates resulted in considerable anti-tumor activity in vivo." (PMID 19948074, 2009). "Treatment of neoplasia must be undertaken rapidly, treatments must be regularly analyzed and drugs binding to albumin may be used with precaution." (PMID 19830148, 2009).
tumor (continued). "In a simple Cox model, the endpoints were found to be significantly associated with tumor size, serum AFP levels of alpha fetoprotein (AFP), total albumin concentration (ALBU), venous infiltration (VENINV), tumor stage (pTNM and AJCC), and the number of tumor nodule (NOTN)." (PMID 19886989, 2009). "Negative hormonal receptor tumours were positively associated with lower albumin concentration (P<0.05), high Ki-67 labelling index (P<0.001) and the presence of CD68+ (P<0.05) and CD8+ (P<0.05) T lymphocytes." (PMID 18797461, 2008). "On univariate survival analysis, age (P<0.10), tumour size (P<0.10), lymph node involvement (P<0.05), albumin (P<0.01), microvessel density CD34+ (P<0.10), locoregional treatment (P<0.01) and systemic treatment (P<0.10) were significantly associated with overall survival." (PMID 18797461, 2008). "Also the patient characteristics age, gender, tumour diagnosis, performance status, creatinine and albumin serum concentration, time since morphine treatment started and survival time after study were similar between the two genetic groups." (PMID 19094200, 2008). "On univariate survival analysis, age (P<0.10), tumour size (P<0.0001), grade (P<0.05), lymph node involvement (P<0.05), hormone receptor status (P<0.01), albumin (P⩽0.001), loco-regional treatment (P<0.01) and systemic treatment (P<0.001) were significantly associated with overall survival." (PMID 17375036, 2007). "On univariate survival analysis, tumour size (P<0.0001), grade (P<0.01), lymph node involvement (P′⩽0.001), hormone receptor status (P<0.0001), albumin (P<0.01), loco-regional treatment (P<0.0001) and systemic treatment (P<0.0001) were significantly associated with cancer-specific survival." (PMID 17375036, 2007). "The hepatocytic nature of the cHCC cell line is further indicated by the activity of the liver-specific enzyme ALT and the expression of hepatocyte markers, like serum albumin, ceruloplasmin, and alpha-fetoprotein, as it is also the case for the human tumor liver cell line HepG2." (PMID 15566568, 2004). "However, regional albumin microspheres produced a significant reduction in tumour and normal liver blood flow and an 80% reduction in mean T/N blood flow ratio." (PMID 1503900, 1992). "The tumour bearing rabbits showed evidence both of increased catabolism and of decreased synthesis and the combination of the two effects resulted in a greater lowering of albumin concentration than was seen in the rats." (PMID 5115834, 1971). "Future directions emphasize the development of multistimuli-responsive albumin nanocarriers, integration with gene editing and immunotherapy, artificial intelligence-guided design optimization, and precision medicine strategies tailored to individual tumor profiles." (PMID 41489768, 2026). "Reduced albumin levels may compromise these functions, thereby intensifying oxidative stress, destabilizing the tissue microenvironment, and weakening immune surveillance—collectively creating a favorable environment for tumor growth and dissemination." (PMID 41566198, 2026). "By reviewing the PET imaging results for the series of [64Cu]­Cu-NODAGA-cLAB-TATEs andof [64Cu]­Cu-NODAGA-cLAB4-scrTATE, we hypothesized that the increasedintegral tumor uptake for these heterobivalent radioligands mightoriginate from the additional SST2-binding of the albumin-boundradioligand." (PMID 40393943, 2025). "However, it remains unclear how serum ALB mediates or modulates tumor number or size expansion at the molecular level." (PMID 40186033, 2025). "Therefore, hepatocyte TM4SF5 might lead to intrahepatic micro-metastasis, expanded tumor size or multifocality via enhanced macropinocytosis resulting from ALB uptake and energetic increases." (PMID 40186033, 2025).
tumor (continued). "As albumin has a long half-life in humans (an average serum half-life of three weeks) through an active recycling mechanism via neonatal Fc receptor binding, long-circulating drug-linker-containing albumin could result in direct tumor uptake and undergoes gradual catabolism to release the payload." (PMID 40005994, 2025). "Similarly, total protein and serum albumin levels were modulated in tumor-bearing mice." (PMID 39880092, 2025). "Preserved ALB stability during early treatment may reflect intact systemic immune competence and reduced tumor-induced catabolism—two important determinants of effective anti-tumor immunity that extend beyond the static nutritional assessment provided by baseline albumin measurements alone." (PMID 41561757, 2025). "In addition, albumin also plays a role in anticancer functions and anti-tumour therapy." (PMID 40045061, 2025). "Abraxane (nab-paclitaxel), an albumin-bound paclitaxel, offers a solvent-free formulation for treating breast cancer, non-small cell lung cancer (NSCLC), and pancreatic cancer that reduces hypersensitivity reactions associated with traditional solvents and provides better tumor penetration." (PMID 40390104, 2025). "In a related study, a cancer drug was loaded into nanoparticles obtained by self-assembly of albumin–polymer conjugate to transport the anti-cancer drug to the diseased area more effectively, and its surface was targeted with ligands suitable for the tumor region." (PMID 39996639, 2025). "In addition, serum albumin can directly inhibit the proliferation of tumor cells." (PMID 40334215, 2025). "Additionally, during the early stages of tumor formation, albumin starts to decline." (PMID 41142623, 2025). "Owing to the role of surface modification in improving the targeting of albumin nanodrugs, prolonging the circulation time in vivo and increasing the selective accumulation of drugs at tumor sites may result in broad application prospects in the field of albumin NPs in oncology." (PMID 39070787, 2024). "Therefore, the use of FA to modify albumin nanomedicine increases specific tumor targeting." (PMID 39070787, 2024). "Consequently, it is reasonable that a low albumin level could favor tumor development and cancer‐related inflammation, which worsens outcome." (PMID 38482966, 2024). "Furthermore, future investigations could delve into the prognostic significance of plasma Fg ratios when combined with other tumor prognostic markers, such as the fibrinogen-to-albumin ratio, F-NLR (fibrinogen and neutrophil-lymphocyte ratio), among others." (PMID 38779081, 2024). "Thus, a combination of these two acute phase proteins, namely the C reactive protein-to-albumin ratio, may more accurately reflect the severity of inflammation, which is believed to be directly correlated with tumor progression." (PMID 39064483, 2024). "Interestingly, the water-soluble IR-783 and ICG are similar with respect to the chemical structures and binding affinity to serum albumin; however, they are very different in the tumor accumulation and retention ability for tumor-specific imaging and treatment." (PMID 38791347, 2024). "Thus, cyanine dyes bound to serum albumin can display higher uptake into tumor cells." (PMID 39138299, 2024). "A low albumin-to-fibrinogen ratio was also associated with a lower rate of complete tumor resection; however, the albumin-to-fibrinogen ratio was not evaluated as a predictive biomarker for complete tumor resection." (PMID 39409916, 2024). "The growing number of studies on albumin NPs as carriers of anti-tumor drugs has led to the development of various methods for drug–albumin conjugation and discovery of many new drugs that can be conjugated with albumin to form NPs, enhancing their anti-tumor activity and targeting." (PMID 39070787, 2024).
tumor (continued). "Hence, albumin stands out as a valuable indicator of hepatic protein synthetic capacity and serves as a meaningful marker for the host’s inflammatory response, playing a crucial role in tumorigenesis from tumor initiation to metastatic dissemination." (PMID 38541140, 2024). "We studied the effect of the following factors on the absorbed dose by tumor and OARs: the competition between labeled and unlabeled ligands in binding to the binding sites, multi-bolus injection instead of a single bolus injection, and the strength of ligand-albumin affinity." (PMID 38252191, 2024). "Additionally, the most important difference between IR-783 and ICG is the presence of the meso-chloride on a cyclohexenyl ring of the heptamethine chain, which could affect the tumor-specific accumulation by the formation of albumin adducts." (PMID 38791347, 2024). "In our study, preoperative and intraoperative variables that may influence leukocytes or albumin, including demographic information as well as the type of pulmonary resection, excision site of lobectomy, and histology of the tumor, were adjusted for baseline differences and selection bias by PSM." (PMID 38630145, 2024). "Consequently, the albumin component of nab-PTX can enhance the tumor penetration." (PMID 38562665, 2024). "Moreover, recent studies have elucidated albumin’s direct effects on tumor biology." (PMID 39600700, 2024). "Furthermore, AFP, albumin and tumor burden were combined to identify the patients who may benefit from liver resection and may be moved forward to BCLC stage A from advanced-HCC patients with PS1 alone." (PMID 37434986, 2023). "Although albumin nanoparticles can efficiently load hydrophobic drugs due to multiple drug binding sites, they may react with proteins in the blood, resulting in reduced uptake of nanoparticles by tumor cells." (PMID 37608298, 2023). "Finally, Cai used a Least Absolute Shrinkage and Selection Operator (LASSO) model with multivariate logistic regression in a single centre moderate volume data set in the context of intraoperative CSF leak prediction, suggesting tumour size and preoperative albumin as key determinants." (PMID 37035179, 2023). "Studies have demonstrated that albumin can attach itself to the gp60 receptor with a molecular weight of 60 kDa, also known as albondin, which is present on the surface of vascular endothelial cells and is transported into the tumor interstitium via transcytosis." (PMID 37836018, 2023). "In addition, albumin also plays an important role in anti-tumor therapy." (PMID 37828259, 2023). "In addition, the intratumoral injection of the albumin-stabilized CeO2 NPs led to contrast enhancements at the tumor site for up to 7 days after injection, and 99% of the injected dose remained at the tumor site, allowing for the monitoring of tumor growth and dynamics." (PMID 37895934, 2023). "High TLS density was significantly associated with less advanced tumour stage, absence of lymphatic/vascular invasion, better serum nutrition parameters (neutrophils count, albumin, neutrophil-to-lymphocyte ratio, and prognostic nutritional index), and prolonged survival." (PMID 37016103, 2023). "Consequently, low albumin levels lead to a decreased probability of active antitumor compounds at the tumor site, which may be one of the reasons a low NRI was associated with poor prognosis." (PMID 36441260, 2023). "Their pharmacokinetic was slightly altered toward a faster tumor uptake due to the larger fraction of free (albumin-unbound) radioconjugate in the blood compared with that of the conjugates modified with the stronger albumin binder (diastereoisomers of [177Lu]Lu-RedFol-1 and [177Lu]Lu-RedFol-3)." (PMID 37686538, 2023). "The immunomodulatory activity of albumin may favor tumor immunity in the tumor microenvironment." (PMID 38024341, 2023).